FAM156A (family with sequence similarity 156 member A)
Synonyms: TMEM29; PRO0659
Gene: Protein-coding gene on chromosome X (52,926,402 to 52,995,564, reverse strand). Ensembl gene ENSG00000268350.
Subcellular location: Membrane
Gene Ontology:
Molecular function: protein binding
Cellular component: nuclear envelope; membrane
Homologues: Orthologues: chimpanzee FAM156A (99% identical), macaque FAM156A (96% identical), dog FAM156A (69% identical), mouse Vcf2 (53% identical), rat Vcf2 (52% identical). Paralogues in human: FAM156B (100% identical).